GSK3B (glycogen synthase kinase 3 beta)
Diseases named in the same sentence as GSK3B in open-access papers (continued):
Sharing a sentence is not in itself a finding about the gene and the disease.
ovarian carcinoma (continued). "Therefore, we predicted that CE might play a role in ovarian cancer by regulating the PI3K/AKT/GSK3B signaling pathway." (PMID 40071097, 2025). "Therefore, we suggest that CE may play an inhibitory role in ovarian cancer by inhibiting the PI3K/AKT/GSK3B signaling pathway." (PMID 40071097, 2025). "Consequently, downregulation of MTSS1 led to excessive accumulation of β-catenin and increased phosphorylation of GSK3β, leading to the translocation of β-catenin to the nucleus, thereby activating the Wnt/β-catenin signaling pathway and ultimately promoting ovarian cancer progression." (PMID 35768865, 2022). "Therefore, we hypothesized that dual targeting of metabolic (GSK3B) and epigenetic (HDACs) pathways might significantly improve anti-tumor treatment and overcome chemoresistance in ovarian cancer." (PMID 32698955, 2020). "Thus, in the present study, the AKT/GSK-3β pathway was investigated to determine whether it played a role in Twist2-mediated cisplatin-resistance in ovarian cancer." (PMID 24944676, 2014). "In this regard, pharmaceutical inhibitors of GSK-3β may have therapeutic benefit in ovarian cancer." (PMID 23840442, 2013). "There were strong positive correlations between expression levels of CXCL8 and p-GSK-3β/p-p70S6K1, showing that p-GSK-3β and p-p70S6K1 levels were important in CXCL8 expression in ovarian cancer." (PMID 39660100, 2025). "In conclusion, our results demonstrate that high levels of ROS in ovarian cancer tissues lead to CXCL8 induction via activation of p70S6K1 and inhibition of GSK-3β." (PMID 39660100, 2025). "Therefore, we conclude that PS VII may hinder the binding of ECM1 to VEGFR2 and inhibit the FAK/AKT/GSK3β signaling pathway in PARP inhibitor-resistant ovarian cancer cells by activating RORα, affecting functions such as glycolysis and angiogenesis, and ultimately improving its resistance treatment." (PMID 38725854, 2024). "APCS-540, a newly developed inhibitor targeting glycogen synthase kinase 3 beta (GSK3B) and histone deacetylases (HDACs), inhibited tumor growth and prolonged survival in an ovarian cancer model." (PMID 36275669, 2022). "This study examines the impact of integrin-linked kinase (ILK), protein kinase B (AKT), glycogen synthase kinase-3β (GSK-3β), and β-catenin signal molecules in SKOV-3 ovarian cancer cells adhered to fibronectin." (PMID 35317111, 2021). "To understand the mechanism by which Hsp90 regulated β-catenin in ovarian cancer cells, we examined the role of AKT/GSK3β signaling in Hsp90-mediated β-catenin expression." (PMID 33738259, 2021). "We showed that β-catenin, GSK-3β, and AKT, and especially ILK are important molecules in the binding of fibronectin to ovarian cancer cells." (PMID 35317111, 2021). "It was reported that ATM mediated the Akt/GSK-3β/Snail signaling pathway in ovarian cancer cells (A2780, Hey, HeyA8, SKOV3, SKOV3ip1, OVCA433 and OVCA429 cell lines), xenograft mouse models of ovarian cancer and high grade serous ovarian cancer patients." (PMID 33802884, 2021). "Data from a recent study showed that inhibition of GSK3B using a small molecule (9ING41) significantly induced apoptosis in SKOV3 and OVCA432 ovarian cancer cell lines and reduced in vivo tumor growth in mice." (PMID 32698955, 2020). "In ovarian cancer, overexpression of miR-195-5p can reduce cisplatin resistance and angiogenesis via PSAT1-depedent GSK3β/β-catenin signaling pathway." (PMID 32201531, 2020). "An ongoing clinical trial (NCT03678883) is testing a GSK3B inhibitor, 9-ING-41, for treating patients with advanced cancers, including ovarian cancer." (PMID 32164570, 2020). "Initially, it was reported that GSK3β was overexpressed in EOC and was positively regulated the proliferation of ovarian cancer cells." (PMID 31829231, 2019). "Based on the protein array data, further ECIS experiments were done to investigate the potential combined effects of a GSK-3β small inhibitor (TWS119) and SLDM on ovarian cancer cell attachment and migration." (PMID 28930226, 2017).
ovarian carcinoma (continued). "We also found that, functionally, CFG significantly suppresses ovarian cancer cell proliferation by cell cycle arrest, apoptosis and senescence and the AKT/GSK-3β pathway is possibly involved." (PMID 28036353, 2016). "Immortalised human ovarian surface epithelium and ovarian cancer cell cells (OVCAR-3) expressed β-catenin, APC, GSK3β and Lef-1." (PMID 14520463, 2003). "The coordinated levels of ROS, p-GSK-3β (Ser9), p-p70S6K (Thr389), and CXCL8 from ovarian cancer may be used as new biomarkers for ovarian cancer development and prognosis." (PMID 39660100, 2025). "In conclusion, the present study demonstrated that Columbianetin acetate could inhibit the proliferation and metastasis of ovarian cancer and induce apoptosis by inhibiting the PI3K/AKT/GSK3B pathway." (PMID 40071097, 2025). "The results of in vitro cellular experiments indicated that CE may inhibit the proliferation and metastasis of ovarian cancer and promote apoptosis by inhibiting the PI3K/AKT/GSK3B pathway." (PMID 40071097, 2025). "In ovarian cancer, it may induce cell apoptosis by the AKT-dependent activation of GSK3β or B cell lymphoma 2 agonists of cell death (Bad)." (PMID 36983018, 2023). "Trichodermin effectively lowered the expression of p-GSK-3β but not GSK-3β, indicating that it restored the activity of GSK-3β in ovarian cancer cells." (PMID 34065149, 2021). "In the OVCAR-3 ovarian cancer cell line, piperine exerted antiproliferative effects by apoptotic cell death, induced arrest of cell cycle at the G2/M phase, and blocking the PI3K/Akt/GSK3β signal transduction pathway." (PMID 33921897, 2021). "The role of GSK3β in EMT suppression is strongly supported by the fact that compounds that reduce serine 9 phosphorylation of the enzyme (like emodin, anthraquinone derived from rhubarb and aloe, and sPSB3 molecule) inhibit EMT in ovarian cancer cell lines." (PMID 32767962, 2021). "Although this observation may suggest an inverse relationship between GSK3β and MMP protein expression, our immunohistochemical data indicate that both GSK3β and MMP-9 are overexpressed in advanced-stage ovarian cancer." (PMID 34023818, 2021). "Dual inhibition of GSK3B and HDACs via APCS-540 showed potent anti-tumor activity in vitro and in vivo, suggesting that APCS-540 may provide a novel treatment option for ovarian cancer, including the platinum-resistant disease." (PMID 32698955, 2020). "Additionally, we found that PS VII potentially hindered glycolysis and angiogenesis in PARPi-resistant ovarian cancer cells by binding and stabilizing the expression of RORα, thus further inhibiting ECM1 and interfering with the VEGFR2/FAK/AKT/GSK3β signaling pathway." (PMID 38725854, 2024). "Overexpression of circFBXO7 in ovarian cancer cells can increase the level of MTSS1 by downregulating the level of miR‐96‐5p, inducing the accumulation and nuclear transport of β‐catenin, as well as phosphorylation of GSK3β, ultimately leading to the deterioration of ovarian cancer." (PMID 39584047, 2024). "In addition to the partial regulation of β-catenin by phosphorylated GSK3β, there may be other downstream factors regulated by circFBXO7/MTSS1 to regulate β-catenin expression or promote β-catenin nuclear translocation in ovarian cancer cells." (PMID 35768865, 2022). "Indeed, in our study, the level of p-GSK-3β, but not total GSK-3β, was downregulated in ovarian cancer when CRIP1 was silenced." (PMID 34413913, 2021). "There were significant increases of β-catenin and GSK3β, while APC was reduced in ovarian cancer compared to the normal ovary." (PMID 14520463, 2003).
tauopathy (87 papers, 2010 to 2026). Neurodegenerative disorders involving deposition of abnormal tau protein isoforms (tau proteins) in neurons and glial cells in the brain. "Tau overexpression in both cell culture and in situ tauopathy models causes this as well, leading to the recruitment of both GSK3b, MARK and fyn kinases, which are all key mediators of Wnt pathway activity and tauopathy-associated tau kinases." (PMID 24151487, 2013). "In the context of macroautophagy loss, GSK3β and phospho-tau are accumulated, reminiscent of early pathology that precedes human tauopathy." (PMID 22998728, 2012). "In particular, GSK3β has been linked to the abnormal phosphorylation of tau in AD, and other tauopathies." (PMID 22347510, 2012). "Because RBX overactivates both PKA and GSK3β associated with tau phosphorylation, rapid tauopathy might ensue despite the favorable effects of CREB activation on the disease." (PMID 39592915, 2025). "Based on these findings, we propose that the spatial proximity of tau to PrPSc, combined with impaired GSK3β inhibition due to loss of PrPC function, may contribute to tauopathy in certain prion diseases." (PMID 40580266, 2025). "GSK3β phosphorylates tau at sites that are associated with tauopathy progression." (PMID 33530349, 2021). "In addition, other emerging targets such as o-GlcNAcase and GSK-3β that associated with tauopathy remain to be explored in tauopathy models." (PMID 35082657, 2021). "Moreover, we also show that the changes in the tauopathy-associated proteins, α-Syn, p-Tau and p-GSK-3β, in the A53T mutant are similar to those which occur in postmortem PD striata." (PMID 21445308, 2011). "On the other hand, Parkin, the product of the PARK2 gene, has been reported to inhibit Wnt signaling, whereas α-Synuclein, a presynaptic protein causal in PD, contributes to GSK-3β-catalyzed Tau (a protein linked to tauopathies, such as AD) phosphorylation (pTau) in PD disease models." (PMID 21752258, 2011). "In this sense, GSK3β may be one of the factors implicated in dysregulation of exon 10 alternative splicing, and in any case, it is known that GSK3β is one of the main kinases implicated in the pathological phosphorylation of some of the tau epitopes associated with tauopathies, including AD." (PMID 40580266, 2025). "Collectively, these findings identify RSK1 as the primary mediator of Tau phosphorylation upon HIV and/or cocaine exposure, and uncover a novel RSK1-driven, GSK3β-independent pathway contributing to Tauopathy." (PMID 42039430, 2026). "This receptor shift leads to dysregulated calcium influx and activation of Tau-related kinases such as GSK-3β and CDK5, which drive pathological phosphorylation at sites including Ser202/Thr205 and Ser396, commonly implicated in tauopathies." (PMID 40806766, 2025). "Other tau enzyme/PTM modulation strategies included in this review and evaluated in primary tauopathy trials were lithium (a GSK3β inhibitor) and salsalate (a tau acetylation inhibitor)." (PMID 40826256, 2025). "We also found that MsA treatment (10–50 μM) significantly reduces tau phosphorylation at Ser404, mechanistically linking PI3K/AKT/GSK3β activation to tauopathy mitigation." (PMID 41007261, 2025). "Reduced tauopathies by targeting Tau mRNA, inhibiting GSK3β, or enhancing tau protein cleavage and degradation." (PMID 39598105, 2024). "Known tau kinases with well-documented roles in tauopathy were also predicted to have differential activity, including GSK3B, CDK5, and CDK5R1." (PMID 38895329, 2024). "GSK3β is a widely expressed multifunctional serine/threonine kinase that phosphorylates Tau predominantly at Ser199, Ser96, and Ser413 in tauopathies." (PMID 36779015, 2023). "GSK3B is a major tau kinase and constitutes a promising therapeutic target against tauopathies like AD." (PMID 37895137, 2023).
tauopathy (continued). "Compound (E)-2f stands out among the synthesized inhibitors as a promising GSK3β inhibitor (IC50 1.7 μM) with a pronounced tau anti-aggregation effect in a cell-based model of tauopathy." (PMID 35455423, 2022). "Together, FX5 protected against neuronal apoptosis by repressing GR/PI3K/AKT/GSK3β pathway-mediated tauopathy and subsequent ER stress in diabetic mice." (PMID 35260821, 2022). "Together, all results demonstrated that FX5 protected against neuronal apoptosis by repressing GR/PI3K/AKT/GSK3β pathway-mediated tauopathy and subsequent ER stress in PA-treated primary neurons." (PMID 35260821, 2022). "Network analysis shows that pioglitazone potentially targets two tauopathy-related proteins (GSK3β and CDK5) in AD." (PMID 35012639, 2022). "It was somewhat surprising to find that GSK3β was inhibited in our study given the major role of GSK3β activation in many tauopathies." (PMID 34203583, 2021). "Reversely, overexpression of REG-1α increased tau hyperphosphorylation through the AKT/GSK3β pathway in the same zebrafish tauopathy model." (PMID 34445171, 2021). "Various strategies have been applied to find novel inhibitors against GSK-3β to reduce the phosphorylation burden of tau and for the management of tauopathies." (PMID 33945025, 2021). "GSK3β, one of the main kinases that phosphorylates Tau, is therefore considered as a key therapeutic target for tauopathy." (PMID 34445171, 2021). "It represents that this scaffold can play a key role in the designing of potent inhibitors against GSK3β for AD and other tauopathies." (PMID 33945025, 2021). "DMF was previously shown to exert a double mechanism of Nrf2 activation by disrupting the KEAP1/Nrf2 interaction and through the glycogen synthase kinase 3 beta (GSK3β)/Nrf2 signaling pathway, in a tauopathy mouse model." (PMID 33096789, 2020). "Phosphorylation of tau at Thr175 and Thr231 and activation of GSK3β are reported features of tauopathy in CTE and CTE-ALS." (PMID 31875105, 2019). "Our proposed studies are serine 285 based phosphorylated tau targeting GSK3α, GSK-3β phosphokinases for AD and other tauopathies." (PMID 30893872, 2019). "Tau hyperphosphorylation at PHF1 epitope, largely mediated by GSK3β, affects microtubule dynamics and NFT accumulation, which is considered a hallmark cytopathology in AD and other tauopathies." (PMID 29982852, 2018). "Both the total protein amount and the activity of GSK3 in tauopathy brain appears to correlate with the progression of neurodegeneration, and over-activation of GSK3β significantly contributes to tau phosphorylation." (PMID 28386764, 2017). "GSK3β activation has induced tauopathy-related phenotypes in mouse models, and GSK3β inhibitors have exhibited beneficial effects against tauopathy and neurodegeneration in tau transgenic mice." (PMID 28228716, 2017). "A key role has been reported for Shaggy, the Drosophila homologue of GSK3β, consistent with the suggestion that GSK3β is a major pathological kinase in human tauopathies." (PMID 24429107, 2014). "The mechanistic contributions of GSK3β in the biGT model to the delay in tauopathy and to clinical phenotype are subject of ongoing studies." (PMID 24498342, 2014). "Together with phosphatases, the synergistic role of CDK5 and GSK3β appears to be essential for tauopathy, and decreased CDK5 inhibits GSK3β function, which affects the disappearance of tauopathy." (PMID 25225483, 2014). "Morin, a polyphenol, present in red wine, has been suggested to have potential for developing therapies for AD and tauopathies by inhibiting GSK-3β." (PMID 22880132, 2012). "That tauopathy occurs in humans was confirmed using postmortem striata from PD patients, where elevated levels of α-Syn, p-Tau and p-GSK-3β were noted." (PMID 21812967, 2011). "Similarly, on another interesting angle, other researchers have tried to target the glycogen synthase kinase-3 beta (GSK-3β) pathway (within ferroptosis) via which tau aggregation is thought to occur in tauopathy." (PMID 39721496, 2025).
tauopathy (continued). "The GSK-3β and CDK-5 pathways are intricately linked to Aβ aggregation, leading to tau hyperphosphorylation through the increased activity of both GSK-3β and CDK-5, ultimately resulting in Aβ-induced tauopathy." (PMID 39061930, 2024). "Furthermore, in mice, Nogo-A increases tauopathy vulnerability to exacerbate AD progression via ROCK/AKT/GSK3β signaling." (PMID 38916730, 2024). "In addition, it has been reported that tauopathy-related changes occur in the diabetic retina, with GSK3β playing a crucial role." (PMID 37754222, 2023). "Here, we used the THY-Tau22 mouse line as an established model of tauopathy to examine whether APPsα may modulate GSK3β and CDK5 kinase activity in vivo and ameliorate Tau-induced pathology and synaptic deficits in vivo." (PMID 36779015, 2023). "FX5 ameliorated synaptic impairment through GR/BDNF/TrkB/CREB pathway, protected against neuronal apoptosis by repressing GR/PI3K/AKT/GSK3β pathway-mediated tauopathy and subsequent ER stress and repressed inflammation through GR/NF-κB/NLRP3/ASC/Caspase-1 pathway." (PMID 35260821, 2022). "Previous in vitro data suggested that Pyk2 activity might enhance GSK3β-dependent Tau phosphorylation and be required for tauopathy." (PMID 35501917, 2022). "In addition, the alteration of GSK3β and mTOR signaling plays a crucial role in tauopathy, which directly or indirectly participated in regulation of tau phosphorylation." (PMID 33967735, 2021). "Inhibitors of GSK3β reduce tauopathy and alleviate neurodegeneration in vivo, and are therefore considered as therapeutic agents highlighting the role of GSK3β in Tau pathology." (PMID 34220449, 2021). "The reduction in tau and p-Tau levels produced by GSK3β inhibitors demonstrated here may also have relevance for pharmacological strategies to prevent tauopathy in early stages of disease." (PMID 34426604, 2021). "In addition, idebenone modulates tauopathy by reducing levels of the tau kinase p-GSK3β, thereby suppressing tau hyperphosphorylation at Thr231." (PMID 34571815, 2021). "The analysis suggests that three compounds can act as best lead molecules against GSK-3β and can act as an anti-Alzheimer compound or could be proposed as potential lead molecules for tauopathies." (PMID 33945025, 2021). "We were interested to see whether the increase in tau pathology, particularly the tau phosphorylation, is regulated by the GSK3β, the key enzyme which is involved in the phosphorylation of tau characteristic to AD/tauopathies." (PMID 32010684, 2019). "Epilepsy has been hypothesized as a tauopathy due to increased levels of P-tau which has been reported to be the result of increased GSK-3β and cdk5 activities." (PMID 30915013, 2019). "This study, for the first time highlights the role of Chico – the ortholog of mammalian IRSs in playing a crucial role in reducing tau hyperphosphorylation and aggregation in our tauopathy models by controlling the downstream tau kinases GSK-3β and ERK and modulating the mTOR/autophagy pathways." (PMID 31427921, 2019). "However, in AD and Tauopathies stressors are assumed to result in Tau hyperphosporylation and GSK3β hyperactivity with decreased phosphatase activity; but the SHSY-5Y cells were not exposed to any stressor, or Tau activator." (PMID 30781361, 2019). "The tau accumulation at or near synapses that accompanies its mislocalization to dendrites and phosphorylation by GSK3b in tauopathy could easily potentiate the sequestration of both GSK3b and tau to late endosomes." (PMID 24151487, 2013). "Indeed, in earlier studies, using a MPTP-treated mouse model which develops tauopathy, we have shown that activated p-GSK-3β co-immunoprecipitates with α-Syn and with pSer396/404 Tau." (PMID 21445308, 2011). "For example, lithium treatment in animal models of tauopathy or TBI has shown some efficacy in reducing tau phosphorylation and pathology by inhibiting GSK3β." (PMID 40349043, 2025).